SLPI (secretory leukocyte peptidase inhibitor)
Diseases named in the same sentence as SLPI in open-access papers (continued):
Sharing a sentence is not in itself a finding about the gene and the disease.
colorectal cancer (continued). "Collectively, these results indicate that evaluation of SLPI expression in patients with colorectal cancer presents a clinically promising biomarker that can facilitate disease risk assessment and severity in patients with colorectal cancer." (PMID 25441765, 2014). "The potential of secretory leukocyte protease inhibitor (SLPI) as a biomarker for colorectal cancer was studied." (PMID 25441765, 2014). "The high expression level of SLPI detected by immunohistochemistry in colorectal cancer showed that it correlated with poorly differentiated colorectal cancer with a TNM stage of III or IV, lymphatic metastasis and distal metastasis." (PMID 25441765, 2014). "Hence, the increased concentration of Akt and p-p65 in the colorectal cancer cell in response to SLPI suppression suggested that SLPI genes regulated CRC cell apoptosis through Akt/NF-κB/PUMA signaling pathways." (PMID 36595102, 2023). "Taken together, these findings demonstrated that suppression of SLPI might repress the growth of human colorectal cancer cells both in vitro and in vivo." (PMID 36595102, 2023). "Indeed, we demonstrated that SLPI protein expression in colorectal cancer (CRC) liver metastases and matched primary tumors is associated with worse outcome, suggesting that SLPI promotes metastasis in human CRC." (PMID 35842496, 2022). "As SLPI was significantly upregulated in colorectal cancer tissues, we sought to determine whether SLPI was essential for the survival of colorectal cancer cells." (PMID 32742768, 2020). "Second, we showed that AKT was involved in SLPI-mediated pathogenesis in colorectal cancer." (PMID 32742768, 2020). "SLPI knockdown effectively reduced colorectal cancer cell growth, migration and invasion in vitro." (PMID 32742768, 2020). "Here, SLPI was knocked down by siRNA in colorectal cancer cell lines HT29 and HT16." (PMID 32742768, 2020). "Last but not least, we propose that AKT may be a novel therapeutic target for colorectal cancer with high SLPI expression." (PMID 32742768, 2020). "Phosphorylation of AKT was significantly reduced after SLPI knockdown in colorectal cancer cells." (PMID 32742768, 2020). "To determine if the difference in SLPI secretion was unique to these TNBCs, we also analyzed conditioned media from a highly metastatic colorectal cancer line Lim6 and its poorly metastatic parental line LS174T, using a similar human antibody array for detection of 500 secreted proteins." (PMID 29312532, 2017). "Compared with normal tissue, SLPI was overexpressed in colorectal cancer tissue." (PMID 25441765, 2014). "Upregulated SLPI correlates with aggressive pathologic characteristics of colorectal cancer; SLPI could be used as an indicator of progression and metastasis in patients with colorectal cancer." (PMID 25441765, 2014). "This study was a prospective, randomized, controlled, clinical trial conducted in 2013 and 2014 to confirm whether SLPI expression correlates with prognosis and metastasis in colorectal cancer patients." (PMID 25441765, 2014). "A prospective, randomized, controlled, clinical trial was conducted in 2013 and 2014 to confirm whether the expression of SLPI correlates with prognosis and metastasis in colorectal cancer patients." (PMID 25441765, 2014). "Importantly, proliferation, migration and invasion of HT29 and HT116 cells were significantly reduced following siRNA-mediated AKT knockdown, suggesting that targeting AKT may be effective for treatment of colorectal cancers with high SLPI expression." (PMID 32742768, 2020). "However, the expression and pathogenetic role of SLPI in colorectal cancer remains elusive." (PMID 32742768, 2020). "Indeed, targeting AKT signaling by siRNA also significantly inhibited tumor cell growth, migration and invasion, suggesting that AKT is the downstream of SPLI and may be a promising therapeutic target in colorectal cancer with high SLPI expression." (PMID 32742768, 2020).
colorectal cancer (continued). "SLPI may be a novel biomarker and therapeutic target for colorectal cancer." (PMID 32742768, 2020). "We performed the cell apoptosis assays to evaluate the synergic effect of SLPI inhibition and PUMA expression in colorectal cancer cells and assessed the expression pattern of c-caspase-3 and Bax, two essential apoptosis biomarkers." (PMID 36595102, 2023). "Here, we showed that the inhibition of SLPI in HT-29 and HCT116 colorectal cancer cell lines resulted in a remarkable increase of PUMA protein expression and consequently reduced the cancer cell viability." (PMID 36595102, 2023). "Inhibition of SLPI supressed the expressions of Akt and fox3a and promote the expressions of PUMA and p65 in colorectal cancer cells." (PMID 36595102, 2023). "To understand the mechanism by which SLPI promoted the protein expression of PUMA in CRC, we investigated the expressions of three essential proteins (Akt, fox3a, and p65) in colorectal cancer cells under siSLPI treatments." (PMID 36595102, 2023). "Next, we sought to investigate the potential crosstalk between SLPI expression and AKT activation in colorectal cancers." (PMID 32742768, 2020). "Collectively, these data demonstrated that the AKT pathway was regulated by SLPI and targeting AKT may be effective for the treatment of colorectal cancer." (PMID 32742768, 2020). "In the present study, our data showed the AKT knockdown was more effective to suppress the migration and invasion of CRC cancer cells than those of SLPI knockdown, suggesting that AKT may be a promising and direct therapeutic target in colorectal cancers." (PMID 32742768, 2020). "Further, targeting AKT also considerably inhibited tumor cell growth, migration and invasion similar to the effects of SLPI knockdown, which indicates that AKT is the downstream of SPLI and might be a novel therapeutic target for colorectal cancer treatment with high SPLI expression." (PMID 32742768, 2020).
Sepsis (7 papers, 2019 to 2025). Sepsis is defined as life-threatening organ dysfunction caused by a dysregulated host response to infection. "Integrating the results of these approaches, C3AR1 and SLPI were identified as key sepsis-associated genes." (PMID 40421173, 2025). "Considerable evidence supports a strong association between C3AR1 and SLPI and sepsis, highlighting their significance in sepsis pathophysiology." (PMID 40421173, 2025). "In humans, plasma SLPI has been found to be increased in sepsis, and to be associated with the degree of organ dysfunction." (PMID 31089838, 2019). "This study confirmed that SLPI levels are significantly elevated in sepsis-induced ALI, further supporting its potential as a biomarker." (PMID 40421173, 2025). "SLPI also played a significant role in sepsis-induced ALI, suggesting its potential as a novel target for personalized medical interventions, targeted prevention, and patient screening." (PMID 40421173, 2025). "The biological role of SLPI expression in sepsis remains only partially understood, but experimental evidence suggests that SLPI protects from detrimental inflammation." (PMID 31089838, 2019). "Moreover, the scRNA-seq analysis demonstrated that the SLPI expression was significantly elevated in immunological organ cells during the early stages of sepsis, a finding further validated in sepsis-induced ALI models." (PMID 40421173, 2025). "Similarly, in the validation datasets GSE69528 and GSE95233, the relative expression of C3AR1 and SLPI in advanced sepsis was significantly higher than in the control group." (PMID 40421173, 2025). "Furthermore, immunofluorescence analysis demonstrated the overexpression of SLPI in the lung tissue during sepsis." (PMID 40421173, 2025). "The expression levels of C3AR1 and SLPI were examined in sepsis datasets." (PMID 40421173, 2025). "The biological significance of circulating SLPI is unknown, but SLPI was detected in the nucleus of peripheral blood monocytes in sepsis patients, and it was shown in vitro that monocytes and B cells internalize exogenous SLPI." (PMID 31089838, 2019). "Compared with those in healthy controls, the levels of CD177, SLPI, OLFM4, and LCN2 were elevated in plasma-EVs from patients with sepsis." (PMID 39901167, 2025). "SLPI can inhibit the inflammatory response and apoptosis of HK2 cells induced by LPS, which may be involved in the protective mechanism of renal tubular cells in the response to sepsis, and is a potential target for the treatment of sepsis-associated acute kidney injury." (PMID 40421173, 2025). "Collectively, the elevation of immuno-suppressors such as PD-L1, SLPI and IL-1R2 and reduction of co-stimulatory molecules such as CD86 contribute to the immuno-suppressive phenotype characteristics of exhausted monocytes observed in clinical sepsis patients." (PMID 34777396, 2021). "SLPI does not influence mHLA-DR expression in vitro, but the observed inverse correlation between these two markers might suggest that SLPI in plasma does not only reflect a pro-inflammatory state or tissue damage, but is possibly linked to sepsis-induced immunosuppression." (PMID 31089838, 2019). "Furthermore, SLPI plays a protective role in endotoxin shock and sepsis, as mice lacking SLPI develop more severe inflammation and increased mortality." (PMID 40496854, 2025).
acute kidney injury (6 papers, 2019 to 2025). Sudden and sustained deterioration of the kidney function characterized by decreased glomerular filtration rate, increased serum creatinine or oliguria. "A study indicated a correlation between septic shock and acute kidney injury (AKI), revealing that the genes PTX3, VMP1, OLFM4, SLPI, TIMP1, LCN2, and S100A9 are strongly correlated with novel biomarkers implicated in the onset and progression of sepsis‐associated acute kidney injury (SSAKI)." (PMID 41394771, 2025). "Previous evidence suggests that SLPI may be a novel biomarker and target candidate for acute kidney injury (AKI), indicated by upregulation of SLPI mRNA levels in AKI allografts as well as elevated protein levels of SLPI in plasma and urine of AKI patients." (PMID 37264340, 2023). "Sepsis may also induce acute kidney injury (AKI), and studies showed that VMP1, SLPI, PTX3, TIMP1, OLFM4, LCN2, and S100A9 genes were markedly correlated with the development and progression of septic-shock-associated AKI." (PMID 36299685, 2022).
prostate carcinoma (6 papers, 2021 to 2026). A carcinoma that arises from epithelial cells of the prostate gland. "Elevated SLPI levels in prostate cancer correlate with a reduced prostate-specific antigen (PSA) progression-free survival." (PMID 41681959, 2026). "In this review, we outline the current evidence regarding the multifaceted functions of SLPI and its expanding role in cancer, focusing primarily on the recently described molecular mechanisms and clinical significance of SLPI in prostate carcinoma." (PMID 41681959, 2026). "The boxplot demonstrated that SLPI is down-regulated in prostate cancer patients, while the CENPF, TOP2A and OR51E2 are up-regulated in prostate cancer patients compared with the normal cohort." (PMID 36937411, 2023). "Volcano plot shows differential expression of DES, HBB, SLPI, and CRISP3 in prostate cancer bone metastases." (PMID 37070095, 2023). "After constructing the prognostic prediction model, SLPI, VSIG2, CENPF, SLC7A1, SMC4, and ITPR2 were finally regarded as the key genes in the prognosis of patients with prostate cancer." (PMID 36937411, 2023).
Allergy (5 papers, 2019 to 2023). An allergy is an immune response or reaction to substances that are usually not harmful. "On the one hand, an SLPI deficiency was shown to augment eosinophil-mediated airway inflammation in experimental mouse allergy models." (PMID 35095834, 2021). "Taken together, these findings suggest that SLPI regulates eosinophil ability to migrate, which may be relevant to eosinophil tissue recruitment under homeostatic and/or allergy-associated inflammatory conditions." (PMID 35095834, 2021). "Eosinophils and secretory leukocyte protease inhibitor (SLPI) are both associated with Th2 immune responses and allergic diseases, but whether the fact that they are both implicated in these conditions is pathophysiologically related remains unknown." (PMID 35095834, 2021). "Previous studies have reported that SLPI as a inhibitor of serine protease is involved in many biological processes, such as antimicrobial action, antiviral activity, allergy reponses, autoimmunity, wound healing, cell proliferation, differentiation and apoptosis." (PMID 34975323, 2022). "SLPI is involved in Th2 immune responses and allergic diseases." (PMID 36431159, 2022). "The histone acetylation process increases the transcription of anti-inflammatory proteins including secretory leukocyte protease inhibitor (SLPI), Glucocorticoid-induced leucine zipper (GILZ) and IκB-α (NF-κB inhibitor), all of which contribute to ameliorating allergy related inflammation." (PMID 31001114, 2019).
chronic obstructive pulmonary disease (5 papers, 2014 to 2025). A chronic and progressive lung disorder characterized by the loss of elasticity of the bronchial tree and the air sacs, destruction of the air sacs wall, thickening of the bronchial wall, and mucous accumulation in the bronchial tree. "SLPI was originally isolated from respiratory secretions from patients with chronic obstructive pulmonary disease (COPD) and downregulation of SLPI was strongly associated with the incidence of COPD." (PMID 32742768, 2020). "In a previous study, human serpins α1-PI, serpinB1, and secretory leukocyte inhibitor (SLPI) blocked NSPs, particularly NE, which reduced inflammation-related severity and excessive elastase-induced tissue damage in a mouse model of chronic obstructive pulmonary disease (COPD)." (PMID 36389172, 2022). "In muco-obstructive lung disorders, such as Chronic Obstructive Pulmonary Disease (COPD) and Cystic Fibrosis, there is an observed elevation in airway SLPI protein concentrations as a result of increased lung inflammation and disease progression." (PMID 39301022, 2024). "In chronic obstructive pulmonary disease (COPD), SLPI is highly expressed in the airway epithelium, where it neutralizes neutrophil elastase, reducing tissue damage." (PMID 40723781, 2025). "In other work, rhinovirus increases the expression of elastase from neutrophils, and decreases expression of the secretory leukocyte peptidase inhibitor (SLPI) and elafin AMPs, enabling secondary Staphylococcus aureus colonization in humans with chronic obstructive pulmonary disease (COPD)." (PMID 26029470, 2014).
colon carcinoma (5 papers, 2013 to 2024). "The suppression of SLPI induced remarkable changes in the expressions of both caspase-3 and Bax proteins, causing caspase-3-inducted apoptosis in colon cancer." (PMID 36595102, 2023). "Hence, the sensitivity of the colon cancer cells to Cisplatin is strictly linked to SLPI and PUMA expressions." (PMID 36595102, 2023). "We found that mouse colon carcinoma cell line treatment with either DKT or butyrate significantly enhanced the expression of SLPI." (PMID 39524440, 2024). "In the present study, we found that SLPI was induced by DKT in a colon carcinoma cell line in vitro, and in the colon of mice in vivo." (PMID 39524440, 2024). "A previous study has revealed the crosstalk between Akt activation and the expression of SLPI in colon cancer." (PMID 36595102, 2023). "A recent study reported that the SLPI knockdown prevents the migration of colon cancer cells in vitro through the modulation of Akt signaling." (PMID 36595102, 2023). "Using the two colon cancer cell lines, HT29 and HCT116, we explored the association between SLPI inhibition and cisplatin sensitivity in the following set of research." (PMID 36595102, 2023). "This section suggested that the SLPI gene might play an essential role in human colon cancer cells by regulating PUMA-dependent reactions." (PMID 36595102, 2023). "Thus, our findings confirm the pivotal role of SLPI in the development of colon cancer and its potential status as a target for therapeutics research." (PMID 36595102, 2023). "Another study determined SLPI as a metastasis promoter and could be utilized as novel therapeutic target for anti-metastatic therapies in breast and colon cancers." (PMID 32076707, 2020). "Thus, suppressing the expression of SLPI in CRCs might be a potential path to promote colon cancer treatment." (PMID 36595102, 2023). "Finally, the lowest level of Ki67 associated with the highest level of c-caspase-3 exhibited by cisplatin + siSLPI groups during the in vivo Immunohistochemical analysis justified that SLPI proteins play crucial roles in regulating cisplatin chemosensitivity of colon cancer cells." (PMID 36595102, 2023). "In addition, a hypothesis has been proposed that a fully human monoclonal antibody that neutralizes SLPI's protease activity may be therapeutically useful for ovarian and colon carcinoma." (PMID 23658834, 2013). "Interestingly, butyrate enhanced the expression of SLPI in a colon carcinoma cell line in vitro, suggesting that DKT increases butyrate-producing bacteria via induction of SLPI expression, which forms a positive feedback loop whereby butyrate induces further SLPI expression." (PMID 39524440, 2024).
head and neck cancer (5 papers, 2013 to 2024). A primary or metastatic malignant neoplasm affecting the head and neck. "These controversies can also be found in HNSCC: By some authors, high SLPI levels in HNSCC were found to have negative effects on invasive tumor growth and metastasis formation, accompanied by low SLPI levels in metastasized head and neck carcinomas." (PMID 39850816, 2024). "SLPI may be a potential biomarker identifying head and neck cancer patients not at risk of developing metastases (SLPI-positive), and those at risk to be infected by HPV (SLPI-negative) and likely to develop metastases." (PMID 23467841, 2013). "On a final note of interest, recent evidence also suggests a role for SLPI in inhibiting human papilloma virus (HPV) infection and subsequent head and neck cancer development." (PMID 24748380, 2014). "As shown, NNMT, FLI1, SLPI, LAMP3, SERPINA1, GAS6, and CD274 have been often used as biomarkers for OSCC or head and neck cancer, while other genes listed have seldom been investigated in oral cancer and may be considered as novel biomarkers for OSCC prevalence and treatment." (PMID 28286742, 2017).
metastatic tumor (5 papers, 2013 to 2021). "In head and neck tumor tissues, for example, lower SLPI concentration was associated with metastatic disease, while this study observed higher SLPI concentrations among OPC cases." (PMID 34214131, 2021). "SLPI is appears in both gene sets indicating its enhanced expression in DTCs as well as metastatic tumor." (PMID 29291741, 2018). "Other researches showed that SLPI, expressed in a range of cancer cell lines, was particularly overexpressed in the highly liver metastatic tumor." (PMID 25954138, 2015). "It is postulated that the absence or repression of the SLPI-antileukoprotease function, as we described here in metastatic tumor specimens, promotes spreading of the tumor by enabling degradation of surrounding tissues by proteases, secreted from the tumors." (PMID 23467841, 2013).